NR1D1 (nuclear receptor subfamily 1 group D member 1)
Diseases named in the same sentence as NR1D1 in open-access papers (continued):
Sharing a sentence is not in itself a finding about the gene and the disease.
bipolar disorder (13 papers, 2009 to 2025). A disorder of the brain that causes unusual shifts in mood, energy, activity levels and the ability to carry out day-to-day tasks. "While further studies are required, so far, variations of Per3 have been associated with age of onset of mood disorders, response to treatment and circadian mood variations and Per 3, Bmal1, CLOCK, Nr1d1 and Nr1f2 have all been linked to bipolar disorder." (PMID 23521808, 2013). "The association of NR1D1 rs2314339 with bipolar disorder and DSPS and the association of PPARGC1B Pro203Ala, rs7732671, with both bipolar and unipolar affective disorders appear the most likely to prove reliable." (PMID 19166596, 2009). "The intronic SNP rs2314339 in NR1D1 met false discovery and empirical family-wise criteria for significant association with the transmission of bipolar disorder (P = 0.0005)." (PMID 19166596, 2009). "In NR1D1, rs2314339 was associated with bipolar disorder (P = 0.0005)." (PMID 19166596, 2009). "REV-ERBα is encoded by the NR1D1 gene, and genetic variations in human NR1D1 loci are associated with bipolar disorder onset and responsiveness to lithium." (PMID 37441675, 2023). "Circadian gene polymorphisms in CLOCK and VIP, and NR1D1, ARNTL and PER3 have previously been associated to human bipolar disorder." (PMID 20856823, 2010). "Lithium, a primary medication for treatment of bipolar disorder, promotes degradation of NR1D1 through inhibition of GSK3, whereas GSK3 phosphorylation stabilizes NR1D1." (PMID 19166596, 2009). "Association studies of NR1D1, RORA, and RORB genes in bipolar disorder." (PMID 25789810, 2015). "Another nuclear receptor, NR2E1, has been reported to be associated with bipolar disorder in a case-control study: there has been brief mention that NR2E1 and NR1D1 may interact in the development of photoreceptors." (PMID 19166596, 2009).
Hepatic steatosis (11 papers, 2021 to 2025). Steatosis is a term used to denote lipid accumulation within hepatocytes. "To further clarify the role of NR1D1 in hepatic steatosis caused by ApoA5 deficiency, we overexpressed NR1D1 in HepG2 cells after knocking down ApoA5 and treated with 500μM palmitic acid for 16 h." (PMID 38505614, 2024). "Consistently, by combining transcriptomics to analyze the pathogenesis underlying fatty liver, we identified the involvement of the nuclear transcription factor NR1D1 that inhibits lipid synthesis, inflammation, and fibrosis." (PMID 38505614, 2024). "Therefore, NR1D1 is a key regulator in both high-fat and alcohol-induced hepatic steatosis." (PMID 38072952, 2023). "Additionally, NR1D1 improves nonalcoholic fatty liver disease (NAFLD) and reduces alcohol-induced hepatic steatosis." (PMID 38072952, 2023). "Furthermore, NR1D1 (nuclear receptor subfamily 1 group D member 1) and ASGR2 GP (asialoglycoprotein receptor) levels increased significantly after the Ramadan fasting period, which may suggest that IF can also have a protective role in hepatic steatosis." (PMID 38068863, 2023).
metabolic syndrome (10 papers, 2018 to 2023). A cluster of metabolic risk factors for CARDIOVASCULAR DISEASES and TYPE 2 DIABETES MELLITUS. "Thus, we inferred that ileal NR1D1 might play a partial role in the modulation of L. reuteri on darkness-induced gut barrier dysfunction and dyslipidemia." (PMID 37422471, 2023). "Heterozygous mice lacked dyslipidemia, a characteristic of Nr1d1 knockout mice and displayed increased whole-body fatty-acid oxidation during periods of inactivity (light cycle)." (PMID 32407314, 2020).
pulmonary fibrosis (9 papers, 2020 to 2025). Chronic progressive interstitial lung disorder characterized by the replacement of the lung tissue by connective tissue, leading to progressive dyspnea, respiratory failure, or right heart failure. "Interestingly, it has been demonstrated that Nr1d1, encoding for Rev-Erbα, an important regulator of the circadian clock, regulates collagen homeostasis and that loss of its activity exacerbated bleomycin-induced pulmonary fibrosis." (PMID 35167499, 2022). "After nebulization, LNPs loading mRNA encoding the nuclear receptor subfamily 1 group D member 1 (NR1D1), a circadian regulatory gene, markedly improve efficiency in treating bronchopulmonary dysplasia (BPD) in rats and pulmonary fibrosis in mice." (PMID 41211661, 2025). "Significantly, emerging evidence underscores the multifaceted influence of Nr1d1 on diverse aspects of physiological and pathological processes encompassing lung inflammation, pulmonary fibrosis, and cardiovascular dynamics." (PMID 39472573, 2024).
Anxiety (8 papers, 2020 to 2025). Intense feelings of nervousness, tension, or panic often arise in response to interpersonal stresses. "The results demonstrate that BPA exposure impairs thigmotactic behavior, a hallmark of anxiety-like behavior, and that NR1D1 activation can ameliorate these effects." (PMID 40559921, 2025). "The largest number of DEGs associated with neurogenesis and making the largest contribution to C_A20 differences are associated with an abnormal anxiety-related response (Nr1d1, Fmr1, Atf2, and Pten)." (PMID 36769363, 2023). "In addition, we evaluated the expression of stress-related genes: glucocorticoid and mineralocorticoid receptors (Nr3c1 and Nr3c2) and Nr1d1, which encodes a transcription factor (also known as REVERBα) modulating sociability and anxiety-related behavior." (PMID 32190129, 2020). "We also identified differentially expressed genes involved in anxiety, mood, emotion (Cartpt, Snap25, Rxfp1, Nr1d1, Sept5), and neuropsychiatric disorders (YWHA-family)." (PMID 40978196, 2025). "The present study explored the role of the circadian clock protein NR1D1 in mediating BPA-induced anxiety-like behavior and brain inflammation early in life." (PMID 40559921, 2025). "In particular, we explored the possible role of nr1d1 in mediating BPA-induced anxiety-like behaviors by examining downstream regulatory targets of nr1d1 and related molecular pathways." (PMID 40559921, 2025). "On the basis of those observations, we can theorize that the Nr1d1 gene is involved in the control of the anxiety level in males with a positive chronic fighting experience." (PMID 36769363, 2023). "Further investigation focused on the role of nr1d1 in BPA-induced anxiety-like behavior." (PMID 40559921, 2025). "It is hypothesized that BPA disrupts the synthesis and metabolism of dopamine by inhibiting nr1d1 transcription, which in turn leads to the manifestation of anxiety-like behaviors in zebrafish larvae." (PMID 40559921, 2025). "Based on these findings, we hypothesize that BPA disrupts nr1d1 transcriptional activity by interfering with estrogen and androgen receptor signaling, ultimately leading to anxiety-like behavior." (PMID 40559921, 2025). "It has been shown that Nr1d1 is one of the circadian genes whose expression may be modulated by a therapeutic dose of lithium, and this finding may be relevant to the treatment of anxiety in neurological disorders." (PMID 36769363, 2023). "The findings emphasize the pivotal function of NR1D1 in mediating the neurotoxic effects of BPA, thereby establishing a connection between circadian dysregulation, neuroinflammation, dopaminergic dysfunction, and anxiety-like behaviors." (PMID 40559921, 2025). "One of them (Nr1d1, nuclear receptor subfamily 1, group D, member 1) features the highest coefficient of correlation between DEGs’ expression and PLS-DA Axis 1 and deals with an abnormal anxiety-related response." (PMID 36769363, 2023).
asthma (8 papers, 2016 to 2025). "Ehlerset al. showed a reduction in expression of BMAL1, PER2 and NR1D1 in bronchial brushings from mild/moderate asthma patients; however, only a single time point was evaluated." (PMID 37404842, 2023). "In a genome-wide ChIP-Seq analysis, the authors were able to identify further interactions of Nr1d1 with the regulation of metabolism and immunity, making Nr1d1 a highly promising target molecule for asthma treatment [37••]." (PMID 36520269, 2023). "Future studies should aim to address how specific clock genes (e.g., Nr1d1 and Nfil3) play an essential role in asthma pathophysiology using chronotherapeutic approaches to delineate observed sex-based differences in severe asthma." (PMID 37664635, 2023). "Overall, there was more variation in the expression of PER2, PER3 and NR1D1 at later time points (16:00 h and 22:00 h) compared to morning time points (04:00 h and 10:00 h) in asthma compared to health." (PMID 37404842, 2023). "Regarding the role of GATA3 in Th2-differentiation, Tiwari and colleagues reported that nuclear receptor subfamily 1 group D member 1 (Nr1d1) suppressed Th2 cell differentiation and attenuated asthma by acting as a transcriptional repressor of the GATA3 promoter [37••]." (PMID 36520269, 2023). "Interestingly, either the overexpression of Nr1d1 or the treatment with its ligand (SR9011) protected mice against lung inflammation in an asthma model (as shown by lung histology, reduced histological scores, IL-4-, IL-5-, and IL-13-levels, as well as reduced GATA3 expression) [37••]." (PMID 36520269, 2023). "Remarkably, the core clock gene nuclear receptor subfamily 1, group D, member 1 (NR1D1, also known as REV-ERB-alpha) resides about 200 kb distal to the top asthma and IBD daVs in chromosomal region 17q21." (PMID 31560728, 2019). "Both PER3 and NR1D1 were significantly rhythmic in those with asthma (p<0.01 and p<0.05, respectively), but not in healthy people." (PMID 37404842, 2023).
atherosclerosis (8 papers, 2009 to 2025). A disease characterized by the build-up of fatty material and calcium deposition in the arterial wall resulting in partial or complete occlusion of the arterial lumen. "Besides Bmal1 and Clock, also the clock genes Nr1d1, Cry1/2, and Rora, have been implicated in atherosclerosis." (PMID 38484032, 2024). "They both identified that NR1D1 regulated the polarization of macrophages and inhibited inflammation in the vasculature during the atherosclerosis progression." (PMID 34956438, 2021). "Previous research have shown that hematopoietic knock down of NR1D1 increases atherosclerosis in LDL receptor knockout mice." (PMID 32328084, 2020). "These researches demonstrated that REV-ERB (including NR1D1 and NR1D2) played an important role in atherosclerosis." (PMID 32328084, 2020). "Besides, a Rev-erba ligand heme which mimicked the overexpression of Nr1D1 promoted M2 marker expression, suggesting that upregulating Nr1D1 may polarize macrophages to an M2 phenotype and that heme is a promising compound for macrophage polarization as well as atherosclerosis treatment." (PMID 30923552, 2019).
diabetes (8 papers, 2009 to 2025). "In the present study, B12 modulated several core clock genes (Bmal1, Cry1, Cry2, Per1, Per3), while other genes were primarily affected by diabetes (Bhlhe40, Hif3a, and Nr1d1)." (PMID 41463345, 2025). "The double actions of EGR1 and NR1D1 in diabetes and osteogenesis indicated their potential roles in the development of diabetic OP." (PMID 36050744, 2022). "Another four TFs (JUN, EGR1, NR1D1, and ATF3) (in italic) were almost involved in all the diabetes-related term and pathways." (PMID 36050744, 2022).
gastric cancer (8 papers, 2020 to 2025). A primary or metastatic malignant neoplasm involving the stomach. "It was reported that the low expression level of NR1D1 was related to poor prognosis in gastric cancer, and NR1D1 was involved in tumor development through suppressing the apoptosis of cancer cells." (PMID 38480634, 2024). "Further study is warranted to determine the mechanisms of reduced Nr1d1 gene expression in gastric cancer." (PMID 36618075, 2022). "NR1D1 and NR1D2 are transcription factors that bind ROREs and act as transcriptional repressors to inhibit the expression of BMAL1:CLOCK, underlining the importance of considering circadian rhythms in gastric cancer development and treatment." (PMID 39062777, 2024). "The mRNA expression of both nuclear receptor subfamily 1 group D member 1 (NR1D1) and nuclear receptor subfamily 1 group D member 2 (NR1D2) is elevated in gastric cancer compared to normal tissue." (PMID 39062777, 2024).
Insulin resistance (8 papers, 2019 to 2025). Increased resistance towards insulin, that is, diminished effectiveness of insulin in reducing blood glucose levels. "The adipose-specific NR1D1 knockout mice were also protected from developing insulin resistance in response to the HFD." (PMID 40654849, 2025). "The adipocyte‐specific NR1D1 knockout mice were also protected from developing insulin resistance in response to the HFD." (PMID 41076654, 2025). "Numerous studies have shown that NR1D1 is a crucial and novel physiological regulator of lipid metabolism, glucose metabolism and insulin resistance." (PMID 38072952, 2023).
rheumatoid arthritis (8 papers, 2017 to 2023). A chronic, systemic autoimmune disorder characterized by inflammation in the synovial membranes and articular surfaces. "For example, NR1D1 was shown to modulate synovial inflammation and bone destruction in rheumatoid arthritis." (PMID 36967480, 2023). "Nr1d1 has been reported to alleviate inflammation during inflammatory diseases such as rheumatoid arthritis and hepatitis." (PMID 36077427, 2022).
Fulminant hepatitis (6 papers, 2020 to 2023). Acute hepatitis complicated by acute liver failure with hepatic encephalopathy occurring less than 8 weeks after the onset of jaundice. "Recent studies in Nr1d1-deficient mice showed that NR1D1 is required for the regulation of NLRP3 expression and activation, thereby inhibiting peritoneal inflammation and fulminant hepatitis." (PMID 33850310, 2021).
glioma (6 papers, 2022 to 2025). A benign or malignant brain and spinal cord tumor that arises from glial cells (astrocytes, oligodendrocytes, ependymal cells). "We still has no clue how these genes get modulated by neutrophil infiltration in brain which might uncover the specific function of CRY2 and NR1D1 on glioma development." (PMID 39043735, 2024). "The differential expression of CCGs in glioma grading confirmed that cluster I genes (ARNRL, NPAS2, and TIMELESS) and CRY1, with cluster II genes (CRY2, DBP, NR1D1, NR1D2, PER2, PER3, and RORA) showed significantly opposite expression trends in brain tissues." (PMID 35832846, 2022). "Besides, the expression of eight CCGs (CRY2, DBP, NR1D1, NR1D2, PER2, PER3, RORA, and TIMELESS) was negatively regulated by methylation and positively regulated by CNV in glioma, which is consisting with previous studies that DNA methylation and CNV can promote abnormal gene expression." (PMID 35832846, 2022).
hepatocellular carcinoma (6 papers, 2009 to 2025). A malignant tumor that arises from hepatocytes. "The nuclear receptor NR1D2 was delayed almost 8h compared to is homolog NR1D1, which is consistent with similar observations in live cell imaging of hepatocellular carcinomas in mouse liver (K. Padmanabhan, personal communication)." (PMID 40424435, 2025). "Aiming at hepatocellular carcinoma (HCC), the interactomic approach between nuclear receptor REV–ERBα (nuclear receptor subfamily 1 group D member 1) and O‐GlcNAc transferase participates in ensuring the rise in contents and O‐GlcNAcylation of TET." (PMID 40599235, 2025).
neuroblastoma (6 papers, 2017 to 2025). Neuroblastoma (NB) is the most common solid, extracranial childhood tumor. "For example, in human neuroblastoma, MYC amplification distorts circadian repressors (NR1D1) and circadian activators (RORA and BMAL1) to cause metabolic rewiring that fuels cancer cell growth and promotes poor patient outcomes." (PMID 37262074, 2023). "Turning to other cancers where BMAL1 is suppressed, MYC amplification in neuroblastoma alters BMAL1 mRNA expression through the induction of NR1D1." (PMID 37262074, 2023). "Neuroblastoma studies demonstrate that NUTM2A-AS1 enhances chemoresistance and metastasis through stabilization of B7-H3, mediated by NR1D1." (PMID 40903777, 2025). "The nuclear receptor NR1D1 has been shown to correlate with MYCN amplification in NB patients and TFAP4 inhibition leads to differentiation of MYCN-amplified neuroblastoma cells, supporting the validity of the inferred target genes." (PMID 38702304, 2024). "In neuroblastoma, elevated NUTM2A-AS1 stabilizes B7-H3 by inhibiting its ubiquitin mediated degradation, a process further driven by its transcriptional activation via NR1D1." (PMID 40903777, 2025).
sleep disorder (6 papers, 2017 to 2025). A change from the patient's baseline sleeping pattern, in the hours slept and/or an alteration/dysfunction in the stages of sleep. "Reductions in the risk alleles for sleep disorders PER1 and NR1D1 were found to have a significant impact on the risk of haemorrhagic stroke in one study." (PMID 41245864, 2025). "Synthetic NR1D1–2 ligands that pharmacologically target both receptors have resulted beneficial for treating sleep disorders as well as metabolic diseases." (PMID 40564218, 2025). "Pharmacologically targeting Nr1d1/2 has been suggested as a potential treatment for sleep disorders and metabolic diseases." (PMID 38732079, 2024).
colon cancer (5 papers, 2020 to 2024). "Consistently, down-regulation of NR1D1 promotes the proliferation of colon cancer cells, while activation of NR1D1 is lethal to cancer cells." (PMID 34330232, 2021).
colorectal cancer (5 papers, 2020 to 2022). A primary or metastatic malignant neoplasm that affects the colon or rectum. "Here, we used the human colorectal cancer (CRC) cell line HCT116 and its knockout variants for different core-clock genes (BMAL1, PER2, NR1D1), to investigate the treatment effect of C. cardunculus lipophilic leaf extract under different clock scenarios." (PMID 36012399, 2022). "In summary, the present study shows that circadian core-clock genes are involved in key cancer properties in colorectal cancer cell lines and proposes the regulation of cell migration, invasion, and metastatic potential by NR1D1 in zebrafish xenografts." (PMID 32244760, 2020). "In colorectal cancer, the transcriptional levels of CLOCK, CRY1, and NR1D1 were upregulated in 1, 1, and 2 datasets, respectively." (PMID 35116071, 2022).